GPR4 (G protein-coupled receptor 4)
Diseases named in the same sentence as GPR4 in open-access papers (continued):
Sharing a sentence is not in itself a finding about the gene and the disease.
tumor (continued). "Evidence suggests that LPC modulates GPR4 activity and potentially mediates both lysophospholipid-dependent and -independent pathways in tumor development." (PMID 40555728, 2025). "Tumor weight was determined ex vivo and shown to be significantly reduced in Gpr4−/− mice compared to WT mice." (PMID 40397803, 2025). "In line with the reduced neutrophil numbers in tumor samples, we observed reduced MMP9 expression in tumor tissue of Gpr4−/− animals compared to WT." (PMID 40397803, 2025). "Our data demonstrate that the endothelial pH‐sensing receptor GPR4 regulates tumorigenesis, tumor growth, and modulates immune cell infiltration to tumor tissue." (PMID 40397803, 2025). "In patients with CRC, GPR4 is increased in tumor tissue, and high GPR4 expression correlates with late‐stage tumors and poor overall survival." (PMID 40397803, 2025). "Associated with this cell influx, we observed increased Fasl mRNA expression in tumor samples from Gpr4−/− mice." (PMID 40397803, 2025). "In both models, the beneficial effects on tumor burden observed in Gpr4−/− mice correlate with an increased presence of NK cells and a reduction in the number of tumor‐associated macrophages and neutrophils." (PMID 40397803, 2025). "We observed slower tumor growth and significantly reduced tumor size in vivo in Gpr4−/− mice compared to WT mice." (PMID 40397803, 2025). "Under acidic conditions, GPR4 activation promotes angiogenesis and enhances vascular permeability, potentially facilitating tumor growth and metastasis while perpetuating acidosis." (PMID 40555728, 2025). "It is a remarkable finding of this study that tumors grown in Gpr4−/− animals exhibit increased tumor tissue infiltration by NK cells and CD3‐positive T cells compared to WT." (PMID 40397803, 2025). "In patients suffering from CRC, GPR4 mRNA and protein are increased as compared to non-tumor tissue, and high expression correlates with late-stage tumors and poor overall survival." (PMID 38514581, 2024). "In a murine model with subcutaneous HCT116 xenografts, tumor progression was reduced when xenografts were depleted of GPR4 with shRNA." (PMID 38514581, 2024). "In the area of tumor biology, it was shown that a GPR4 antagonist (3b) partially suppressed acidic-pH-induced expression of the growth hormone and prolactin in MtT/S pituitary tumor cells." (PMID 39336742, 2024). "In melanocytes, upon overexpression of the BRAFV600E oncogene, disruption of GPR4 was found to be highly selected, suggesting a tumor-suppressor role." (PMID 39336742, 2024). "i) GPR4 is highly expressed in human tumors and promotes the proliferation of tumor cells and angiogenesis in an acidic microenvironment." (PMID 38505262, 2024). "GPR4 knockout alleviated intestinal inflammation, reduced tumor angiogenesis, and impeded CAC development." (PMID 37894341, 2023). "Consistently, GPR4 KO mouse tumors showed reductions in tumor angiogenesis when compared with WT tumors in the AOM/DSS mouse model." (PMID 37894341, 2023). "Our observations in this study suggest that the decrease in microvessel density in tumors of GPR4 KO AOM/DSS mice is associated with increased tumor cell death and reduced tumor cell proliferation caused by the prevention of adequate tumor vascularization." (PMID 37894341, 2023). "In this study, we employed the double immunolabeling of GFP and CD31 to detect GPR4 expression in tumor vascularization." (PMID 37894341, 2023). "The quantification of Ki67-positive cells revealed a ~two-fold decrease in proliferating tumor cells in GPR4 KO AOM/DSS mouse tumors." (PMID 37894341, 2023). "Next, we evaluated Ki67 as a proliferation marker to assess tumor cell proliferation in the WT and GPR4 KO AOM/DSS mice." (PMID 37894341, 2023). "Studies have demonstrated a role for GPR4 in promoting angiogenesis and tumor growth in the porous tissue implant and orthotopic tumor models." (PMID 37894341, 2023).
tumor (continued). "The WT mice had an average tumor number of 7.4, whereas the GPR4 KO mice had an average of 5.1, demonstrating a 45.1% increase in tumor number in the WT over GPR4 KO AOM/DSS mice." (PMID 37894341, 2023). "It seems that, depending on the tumor microenvironment and cellular context, GPR4 can be involved in both tumor-promoting and tumor-suppressing processes." (PMID 34440817, 2021). "GPR4-deficient mice showed a significantly reduced angiogenic response to VEGF, which accordingly led to a reduction in tumor growth in orthotopic models." (PMID 32948783, 2020). "For example, activation of GPR4 in acidic conditions reduces migration, invasion and the metastatic potential of tumours, while repressing vascular growth; this GPCR activates the Gs, G12/13 and Gq G-protein pathways." (PMID 36046070, 2020). "For MM and NCN tumor tissue, epidermal and dermal tumor cells were distinguished in terms of GPR4 expression." (PMID 32948783, 2020). "The objective of this study was to explore the role of GPR4 in acid exposure and tumor angiogenesis in SCCHN." (PMID 27078157, 2016). "GPR4 was amplified in 9/12 samples and upregulated in the tumor tissues compared with the peri-tumor normal tissues." (PMID 27078157, 2016). "In the Ad-null and Ad-GPR4-FaDu cells, the vascular densities surrounding the tumor were 8.46%, and 16%, respectively." (PMID 27078157, 2016). "The GPR4 protein expressed at higher levels (red arrows) in the tumor cells compared with the epithelial cells of peri-tumor normal tissues." (PMID 27078157, 2016). "Decreased tumor weight in Gpr4−/− mice was confirmed at postmortem." (PMID 40397803, 2025). "We used MC38‐luciferase cells to monitor tumor burden in Gpr4−/− mice vs. WT." (PMID 40397803, 2025). "Next, we evaluated the tumor burden in WT mice compared to Gpr4−/− mice in the AOM/DSS model." (PMID 40397803, 2025). "GPR4 is predominantly expressed in ECs and to some degree in pericytes, and the available data underscore the important role that the local microvascular system plays in tumor growth." (PMID 40397803, 2025). "GPR4, a prominent member of proton-sensing GPCRs, commands particular attention due to its ubiquitous expression and crucial roles in endothelial function, tumor biology, and metabolic acidosis regulation." (PMID 40555728, 2025). "Vascular normalization afforded through GPR4 inhibition may normalize tumor extracellular pH and stabilize IL2 protein." (PMID 40397803, 2025). "GPR4 is highly expressed in vascular endothelial cells and plays a role in tumor angiogenesis." (PMID 39336742, 2024). "For example, in orthotopic tumor models of breast and colon cancer cells, GPR4 is activated after pH reduction and promotes tumor growth and pathological angiogenesis through p38-mediated secretion of interleukin-6 (IL-6), IL-8, and vascular endothelial growth factor-A (VEGF-A)." (PMID 38505262, 2024). "Conversely, GPR4 knockout mice showed inhibited tumor growth." (PMID 38505262, 2024). "In addition to cancer cells, the function of GPR4 in stromal cells in the tumor microenvironment has been studied." (PMID 39336742, 2024). "Further studies are needed to confirm whether GPR4 can affect tumor progression by changing calcium signaling." (PMID 38505262, 2024). "In summary, current evidence supports that GPR4 promotes tumor proliferation and angiogenesis." (PMID 38505262, 2024). "We next characterized the expression profile of GPR4 in the AOM/DSS mouse tumor model." (PMID 37894341, 2023). "Reduced GPR4 signaling impairs the growth of murine tumor allografts." (PMID 36902589, 2023). "Furthermore, a significant reduction in breast and CRC tumor growth in GPR4 knockout mice and in vitro CRC cell proliferation caused by GPR4 knockdown has been observed." (PMID 37894341, 2023).
tumor (continued). "Furthermore, using a double fluorescent stain with GFP and the endothelial marker CD31, we observed that GFP expression was predominately detected in the endothelial cells (ECs) of blood vessels in the tumor tissue of GPR4 KO AOM/DSS colons." (PMID 37894341, 2023). "The role of GPR4 in angiogenesis and tumor biology seems to be more contradictory." (PMID 34440817, 2021). "High expression of GPR4 is seen both within liver tumor tissue and at the tumor margins." (PMID 33809908, 2021). "It remains to be investigated if these substances could potentially be used as an anti-inflammatory treatment in patients, or if the pleiotropic effects of GPR4, especially in tumor biology, are confounding factors for the clinical use of GPR4 inhibitors." (PMID 34440817, 2021). "This suggests that GPR4 may have both anti and pro-tumour effects dependant on cell type, which may limit the clinical application of compounds that increase or limit GPR4 activation, until further research clarifies the possible mechanisms involved." (PMID 36046070, 2020). "Possibly, cAMP-independent signalling may be more important for the action of GPR4 (see introduction), this includes also slow, genomic mechanisms which only become relevant under chronic conditions, such as during tumour formation." (PMID 29894771, 2018). "Tumor growth in GPR4−/− mice is abrogated, because of reduced angiogenesis, suggesting that acidic pH-stimulated GPR4 may regulate endothelial cell growth." (PMID 24381558, 2013). "Collectively, both tumor-promoting and tumor-suppressing effects of GPR4 have been reported, which may depend on cell type and biological context." (PMID 24367336, 2013). "However, the observation that the NK cell supporting cytokine IL2 is significantly increased in tumor tissue of Gpr4−/− animals compared to WT may hold at least part of the response." (PMID 40397803, 2025). "However, the effect of GPR4 on tumor invasion and metastasis may act as both a tumor metastasis promoter and a tumor metastasis suppressor, which may be related to tumor cell type." (PMID 38505262, 2024). "Furthermore, GPR4 knockout reduces tumor angiogenesis and growth." (PMID 37894341, 2023). "Flow cytometry analysis of the tumor infiltrate confirmed an increase in both NK and NKT cells in the tumors of Gpr4−/− mice." (PMID 40397803, 2025). "The acidic pHe sensing system of the cells such as proton sensing GPCRs such as GPR4, TDAG8, and OGR1 is a good strategy for tumor therapy." (PMID 39372863, 2024). "The percentage of tumor necrosis areas between the WT and GPR4 KO AOM/DSS tumors was ~ 2.4-fold higher in the GPR4 KO AOM/DSS tumors compared with the GPR4 WT AOM/DSS tumors." (PMID 37894341, 2023). "G protein-coupled receptor 4 (GPR4) is one of the four receptors of the OGR1 subfamily, which is widely distributed in various human tumor tissue cells and participates in and influences tumorigenesis and development." (PMID 37816979, 2023). "Together, these findings suggest that GPR4 and CD105 are useful HCC tumor markers and potential therapeutic targets." (PMID 33809908, 2021). "Similar to GPR4, OGR1 has several contrasting effects, in tumor biology, whereas its role in cardiovascular physiology and its role as a mechanoreceptor seems to be more prominent and distinct compared with the other proton-sensing GPCRs." (PMID 34440817, 2021). "There is a strong association between GPR4 expression and MVD, and sites of high GPR4 expression correspond with CD105 expression hotspots among hepatic sinusoids and endothelial cells surrounding tumor tissue (within a 2 cm margin)." (PMID 33809908, 2021). "GPR4 and OGR1 (related to SPC), which sense the acidic tumor microenvironment that results from cancer metabolism, regulate cancer cell proliferation and metastasis, inflammation including immune cell function, and angiogenesis." (PMID 31683697, 2019).
tumor (continued). "Taken together, results from the heterotopic MC38 model showed that the absence of GPR4 in host animals significantly attenuated tumor progression." (PMID 40397803, 2025). "The absence of GPR4 significantly attenuated tumor progression in the colon of mice, and this result correlated with increased cytotoxic cell activity and reduced presence of tumor‐associated macrophages and neutrophils." (PMID 40397803, 2025). "Bone marrow MSCs and fibroblasts are known to express high levels of acid sensing receptors [acid-sensing ion channel 3 (ASIC3), ASIC4, G protein-coupled receptor 4 (GPR4), and GPR65], and become activated by the acidic environment created by bone metastatic tumor cells." (PMID 29747461, 2018). "In SCCHN, the correlation between acid exposure, tumor angiogenesis and GPR4 has not been well studied." (PMID 27078157, 2016). "Our data suggest that the absence of GPR4 in the tumor‐bearing host may affect tumorigenesis through two parallel events: decreased inflammation and increased anti‐tumor responses." (PMID 40397803, 2025). "In the intricate landscape of the tumor microenvironment, the signal transduction triggered by lactate stimulation mainly relays on the lactate receptor HCAR1 (GPR81), and proton-sensing G-protein coupled receptors (GPRs), including GPR4, TDAG8 (GPR65), OGR1 (GPR68), and G2A (GPR132)." (PMID 38576043, 2024). "On the other, GPR4 overexpression in murine melanoma cells reduced their migratory ability in vitro and suppressed pulmonary metastasis when injected intravenously in mice, although it did not affect the formation of a primary tumor when these cells were administered subcutaneously." (PMID 33113952, 2020).
cancer (21 papers, 2011 to 2025). A tumor composed of atypical neoplastic, often pleomorphic cells that invade other tissues. "As acidosis is closely associated with inflammation, ischemia, cancer, and other diseases, the GPR4 proton-sensing receptor family may play a role in these pathological conditions." (PMID 22110680, 2011). "While GPR4 is predominantly expressed in endothelial cells, previous studies have also highlighted a possible direct role for GPR4 in regulating cancer cell behavior." (PMID 40397803, 2025). "In patients suffering from CRC, high expression levels of GPR4 correlate with late-stage cancer and poor overall survival." (PMID 38514581, 2024). "Overall, GPR4 has been reported to diminish and promote malignancy, which is dependent on cancer and cell type." (PMID 39336742, 2024). "Depending on the cancer type and context, both pro- and anti-tumorigenic effects of GPR4 have been reported." (PMID 39336742, 2024). "Regarding cancer cells themselves, it was shown that ectopic expression of GPR4 in murine 3T3 cells induced malignant transformation." (PMID 32948783, 2020). "More recently, the analysis of public RNA sequencing data on 23 different kinds of tumors showed that most cancers present a differential expression of GPR4, but only a few reached statistical significance." (PMID 33113952, 2020). "A decrease in extracellular pH promotes growth, migration, invasion, and metastasis of cancer cells in an acidic environment via GPR4, GPR65 (TDAG8), GPR68 (OGR1), and GPR132 (G2A), which are pH-sensing G protein-coupled receptors (GPCRs)." (PMID 32998265, 2020). "In the current study, we hypothesized that MMP9, a potential biomarker for several cancers and a protein with an important role in cancer progression, would be reduced in the AOM/DSS model of colitis‐induced cancer in Gpr4‐deficient animals." (PMID 40397803, 2025). "The pro-inflammatory role of GPR4 has been established in several organ systems, such as the nervous, cardiovascular, respiratory, renal, skeletal, skin, and gastrointestinal systems, and in cancer." (PMID 39336742, 2024). "A recent study showed that activation of GPR4 by an acidic pH increased the expression of inflammatory chemokines and adhesion molecules in lymphatic endothelial cells and promoted cancer cell metastasis, which were both attenuated by GPR4 knockdown and inhibition." (PMID 39336742, 2024). "The data suggest that the inhibition of GPR4 may be exploited as a potential approach to anti-inflammatory and anti-cancer therapy." (PMID 37894341, 2023). "Recent efforts aimed at developing GPR4 modulators have given rise to an specific orally-active compound that will probably help to characterize the potential of this receptor as a new therapeutic target against cancer." (PMID 33113952, 2020). "Functional studies show divergent roles of GPR4 in different types of cancer." (PMID 33113952, 2020). "The average expression intensities of GPR4 in multiple cancers." (PMID 27078157, 2016). "Similar effects of cancer metastasis suppression by GPR4 and OGR1 may be due to the fact that they share the highest homology between the members of the proton sensing GPCRs." (PMID 24367336, 2013). "Besides, GPR4 regulated cell metastatic ability and apoptosis in some types of cancers." (PMID 36874362, 2023). "This indicates that GPR4 may be involved in cancer-related angiogenesis." (PMID 27078157, 2016). "Tumors in Gpr4−/− mice show reduced growth relative to WT, suggesting that cells within the microenvironment constrain MC38 cancer cell growth in this model." (PMID 40397803, 2025). "Thus, GPR4 activity may contribute to oncogenic progression across a many cancers." (PMID 40397803, 2025). "Herein, we review the current research progress pertaining to these proton-sensing GPCRs, including GPR4, GPR65 (TDAG8), and GPR68 (OGR1), in inflammation and cancer." (PMID 39336742, 2024).
cancer (continued). "Proton-sensing GPCRs, TDAG8, GPR4, and/or OGR1 are expressed in a large number of human cancers, including stomach cancer, prostate cancer, and CRC." (PMID 38514581, 2024). "GPR4 has been shown to promote angiogenesis by regulating the VEGF pathway in both ischemic tissues and cancer tissues." (PMID 37894341, 2023). "This is the first study on pH-GPCRs in peritoneal carcinomatosis, which shows lower expression of GPR4 and GPR68 as compared to other pH-GPCRs in this type of cancer." (PMID 36902589, 2023). "G-protein coupled receptor 4 (GPR4) is a type of GPCR that is activated by protons and is involved in cancer-related angiogenesis." (PMID 35625966, 2022). "The binding of leucine-rich repeat-containing G-protein-coupled receptor 4 (LGR4) to its receptor R-spondin was reported to promote the proliferation and metastasis of cancer cells." (PMID 36091041, 2022). "The recently published GPR4 blocker, NE 52-QQ57, represents a promising new family of drugs, because GPR4 is one of the potential targets in cancer therapy and inflammatory responses." (PMID 29894771, 2018). "Recent studies show that the pH-sensing GPCRs, including GPR4, GPR65 (TDAG8), GPR68 (OGR1), and GPR132 (G2A), regulate cancer cell metastasis and proliferation, immune cell function, inflammation, and blood vessel formation." (PMID 24367336, 2013). "In the present study, we demonstrated that OGR1, but not GPR4, suppressed cell migration of MCF7 cells, extending the migration inhibitory effect of OGR1 to an additional cell lines and cancer type." (PMID 23663350, 2013).
infection (2 papers, 2020 to 2025). The state of being infected such as from the introduction of a foreign agent such as serum, vaccine, antigenic substance or organism. "To determine if the GPR4 antagonist had anti-SARS-CoV-2 effects when administered post-infection, we infected Vero E6 cells with virus for a 1-h adsorption period and then treated the cells with the GPR4 antagonist for 24 h." (PMID 40703349, 2025).
inflammation (2 papers, 2023 to 2025). Aberrant reaction of the microcirculation characterized by movement of fluid and leukocytes from the blood into extravascular tissues. "To investigate the interplay between GPR4 and OGR1 in the development of acute intestinal inflammation we used the well-characterized DSS model." (PMID 40004018, 2025).
respiratory disorders (1 paper, 2025). "The high expression and involvement of GPR4 in inflammation, angiogenesis, respiratory disorders, renal dysfunction, and cancer position it as a promising therapeutic target." (PMID 40555728, 2025).